MTOR (mechanistic target of rapamycin kinase)
Diseases named in the same sentence as MTOR in open-access papers (continued):
Sharing a sentence is not in itself a finding about the gene and the disease.
tumor (continued). "Furthermore, the expression of regulated in development and DNA damage response 1 (REDD1), an inhibitor of the mechanistic target of rapamycin (mTOR), is upregulated in hypoxic TAMs and inhibits glycolysis, which may affect TAM motility in hypoxic tumor regions." (PMID 34476174, 2021). "Moreover, no AMPK-mediated inhibition of the mTOR-p70S6K pathway was observed in the tumor tissue." (PMID 34884872, 2021). "However, except for the well-characterized upstream mTOR activators (PI3K25, Grb238, and HRAS39), a direct function for most mTOR components, including the ones found in our hit list, in the context of TNBC tumor development remains unknown." (PMID 34031411, 2021). "Briefly, mTOR could regulate the expression of cytokines/chemokines, including interleukin-10 (IL-10) and transforming growth factor-β (TGF-β), and/or membrane receptors, such as cytotoxic T-Lymphocyte protein 4 (CTLA-4), PD-L1 and PD-1, to modulate tumor immune cells." (PMID 34458019, 2021). "Future rigorous clinical studies, aimed at addressing the tumor heterogeneity, the interaction with the microenvironment, as well as diverse posology adjustments, are needed—which might unravel the therapeutic efficacy and response prediction of an RTK/PI3K/mTOR-based approach." (PMID 34063168, 2021). "Also, data regarding PTEN status or PI3K-Akt-mTOR alteration were not derived from pure tumor cells, but from the tumor mass containing tumor cells as well as a small subset of stromal cells, infiltrating immune cells, whose confounding effect cannot be ruled out." (PMID 33874915, 2021). "Indeed, popular targeted therapies for RMS include mTOR and Hedgehog inhibitors and RTK-specific monoclonal antibodies or small-molecule inhibitors but, while an initial response is observed with these treatments, the disease often continues to progress and/or tumour drug-resistance develops." (PMID 32098189, 2020). "However, other pathways including mammalian target of rapamycin (mTOR), phosphatidylinositol 3-kinases (PI3K)-Akt, Wnt/β-catenin, nuclear factor-κB (NF-κB), mitogen-activated protein kinases (MAPK), and NADPH oxidase (NOX) facilitate the adaption of tumor cells to hypoxia." (PMID 33302971, 2020). "Therefore, chronic exposure to everolimus could create negative feedback loops with reactivation of Akt-mTOR signaling, driving the mitotic circle forward and blocking those proteins with tumor-suppressive properties (p19, p27)." (PMID 32512849, 2020). "However, the primary effects of this gene on oncogenesis through control of the PI3K–AKT–mammalian target of rapamycin (mTOR) pathway might not be the only avenue by which PTEN affects tumour progression." (PMID 32327707, 2020). "Furthermore, mTOR-RICTOR could control cystine uptake and glutathione metabolism by directly phosphorylating xCT, enabling tumor cells to buffer reactive oxygen species (ROS) and transform resources from proliferation to survival processes when the extracellular environment dramatically changes." (PMID 32041519, 2020). "This may indicate that although both mTOR substrates can be suppressed by RAD001 in vitro, the anti-tumor effects observed in our CEA424-SV40 T antigen transgenic mouse model system may dependent more on the inhibition of p70S6K, or some other feedback mechanisms help rescue the tumor cells." (PMID 32373532, 2020). "Additionally, the activation of short-form Ron, AKT-mammalian target of rapamycin (mTOR), or the Wnt-β-catenin signaling pathway and the over-expression of STAT3, cyclooxygenase-2, c-Myc, (ATP)-binding cassette (ABC) gene 1, or heat shock protein 27 can also induce tumor resistance to MET-TKIs." (PMID 32435640, 2020).
tumor (continued). "This raises the question whether or not the combination with a clinically approved treatment, such as with the mTOR inhibitor compound everolimus, could augment effects of oncolysis in our panel of human NET/NEC cell lines, thus opening up novel treatment procedures for this unique tumor entity." (PMID 32631270, 2020). "However, the inhibition of mTOR with an mTOR inhibitor (everolimus) reduced the tumor growth in xenograft mice, but did not shrink the tumor size, probably due to the increased activity of Akt and ERK by this drug, confirming the c-MET-dependent resistance of the tumor." (PMID 31416195, 2019). "These could help to identify new markers beside mTOR activity characterisation—such as FASN, CPT1a, ACSS2—or find good mitochondrial function markers (e.g. TOM20, NRF1), and to assign the metabolic expression profile of tumours before starting treatments in patients." (PMID 30574020, 2018). "Dual PI3K/mTOR inhibitors show less toxicity in patients, furthermore, their clinical efficacy is mainly related to genetic alterations e.g. PI3KCA, PTEN mutations which could suggest possible mTORI sensitivity of tumours and could not lower the recurrence." (PMID 30574020, 2018). "Interestingly, the β1-integrin has recently been reported to control skeletal metastasis by crosstalking with the Akt–mTOR pathway, which might explain why chronic TEM application is coupled to both increased tumor invasiveness and increased β1-integrin expression." (PMID 30200497, 2018). "To determine whether the tumor suppressive effects of SNORA74B knockdown are mediated by PHLPP, we knocked down PHLPP by shRNA and examined the effects of SNORA74B silencing on the activation of members of AKT/mTOR signaling pathway, as well as on cell viability, cell cycle, and apoptosis." (PMID 28212545, 2017). "Since mTOR signaling is strongly involved in regulation of cellular metabolism and aggressive growth behavior of GBM cells requires adaptation processes to metabolic changes in the tumor microenvironment, we examined whether sCPE may also affect metabolic pathways in GBM cells." (PMID 28978054, 2017). "NDUFA4L2 may interact with 14 tumor-related proteins, participate in growth and death processes and be involved in ccRCC-related pathways, such as insulin-like growth factor 1 (IGF-1), mammalian target of Rapamycin (mTOR) and phosphoinositide 3 kinase serine/threonine protein kinase (PI3K/AKT)." (PMID 29158991, 2017). "However, p-mTOR overexpression was clinically significant; indeed, GC patients with p-mTOR overexpression poorer differentiation, higher possibility of lymph node metastasis, deeper wall invasion and later tumor stage compared with p-mTOR negative patients." (PMID 29233126, 2017). "Thus, it is possible that co-targeting mTOR may potentially enhance rather than reduce the anti-tumor activity of IO agents." (PMID 28822012, 2017). "Also, our lab previously reported that SLC34A2 was down-regulated in human NSCLC tumor tissues and cells, and might act as tumor suppressor by inhibiting the growth, invasion and migration of lung cancer cells through the PI3K-Akt-mTOR and Ras-Raf-MEK-ERK signaling pathway." (PMID 26910912, 2016). "However, in contrast to other tumours driven by upstream mutations affecting the very same pathway, loss of TSC function manifests as highly apoptotic non-malignant neoplasia suggesting that exorbitantly high mTOR activity in TSC-/- cells impedes full blown tumour development." (PMID 27863419, 2016). "However, agents targeting EGFR or mTOR did not elicit anti-tumor responses in the BD-138T PDCs." (PMID 27438149, 2016). "Importantly, the central functional role of rpS6 opens up the possibility to exploit the measurement of rpS6 expression levels as a predictive biomarker that prognosticates whether a tumor will respond to pharmaceutical mTOR inhibition or not." (PMID 26506236, 2016).
tumor (continued). "Since the PI3K-AKT-mTOR can also become activated in the absence of PIK3CA mutation, for example through loss of PTEN, or mutations in AKT and MTOR, it is hoped that the clinical activity of PI3K inhibitors may not be limited to PIK3CA mutant tumours." (PMID 27765909, 2016). "To uncover the mechanism of rapamycin-mediated inhibition of mTOR signaling in NPC cells, we investigated whether the signaling was activated in CSCs in secondary NPC tumors in BALB/c nude mice and whether rapamycin could inhibit tumor growth and NPC CSCs in vivo." (PMID 26202311, 2015). "Therefore, as ACSL4 regulates ERα expression and the mTOR pathway, our results provide evidence that ACSL4 could be also an interesting target, in combination with 4-OHTAM, to restore tumor hormone dependence in tumors with poor prognosis and low survival rates." (PMID 26536660, 2015). "Thus, these preclinical data suggest that MEK and PI3K/mTOR inhibition may delay tumor growth but may not affect tumor size regression and is likely to be inferior to MEK and PI3K inhibition." (PMID 26404261, 2015). "In addition to inhibiting activation of the insulin-dependent PI3K/Akt/mTOR pathway, several studies have shown that metformin inhibits mTOR activation through activation of AMPK, which is also a critical mechanism of metformin in exerting its anti-tumor effects." (PMID 25879666, 2015). "Furthermore, similar to progerin and klotho, approaches that target mTOR signalling may have beneficial effects on the human lifespan independent of potential effects on tumour formation." (PMID 25388238, 2015). "As the PI3K/AKT/MTOR pathway is essential for hepatic gluconeogenesis, everolimus may counteract hypoglycemia independent of its anti-tumor effect by enhancing the expression of liver gluconeogenic enzymes and nuclear recruitment of gluconeogenic transcriptional regulators." (PMID 25298880, 2014). "Because in our study the tumor inhibitory effects of protein restriction were partially independent of mTOR, we assessed whether epigenetic modifications, that are known to be associated with PCa progression, were modified by protein restriction in the LuCaP23.1-CR model." (PMID 24353195, 2013). "Thus, lack of in vitro tumor cell apoptosis may not accurately reflect the in vivo situation where tumor cell survival can be regulated by the microenvironment which itself may be impacted by mTOR inhibitors." (PMID 23533410, 2013). "However, since MPNST are not homogeneous tumours and may harbour different genetic alterations that might influence the Akt/mTOR pathway further studies are needed to clarify the impact of Pten status for therapeutic strategies." (PMID 23139750, 2012). "Furthermore, p-AKT, p-mTOR, p-4E-BP1, and cyclin D1 expression levels in epithelial ovarian and peritoneal tumors were shown not to be associated with partial/complete tumor responses to Temsirolimus, however cyclin D1 expression seemed to correlate with PFS ≥6 months." (PMID 22970424, 2012). "Thus, the profound effects on tumor growth may have been a consequence of perturbation of glucose homeostasis and hormone levels leading to the indirect inhibition of mTOR by decreasing activation of IR/IGF-IR and AKT upstream of mTOR." (PMID 22203527, 2011). "Acquiring matched PK and PD (tumor and surrogate PBMC measurements) for all dosing cohorts in this study demonstrates a unique attribute of the comparative approach that can aid in the discovery and validation of novel biomarkers that may predict response to mTOR inhibitors." (PMID 20543980, 2010). "In tumours without p-mTOR expression, another signalling pathway, such as Erk, may be activated." (PMID 19223902, 2009).
tumor (continued). "Importantly, normal SVZ cells responded in a different way; indeed, by chemically stabilizing HIF-1α, REDD1 was transiently upregulated and Akt/mTOR pathway was not inhibited, unlike in tumor cells, following exposure to high oxygen tension, and Akt and Stat3 were eventually upregulated by CoCl2." (PMID 19587783, 2009). "Therefore, clinical response criteria such as CT-scan-based RECIST or evaluation of treatment response by studying tumour vascularisation may not apply to mTOR-inhibitor therapy." (PMID 19436299, 2009). "Here we found that by stabilizing HIF-1α with CoCl2, inhibition mTOR pathway was maintained following acute high oxygen exposure on tumor cells, and this may occur through a negative feedback loop dependent on HIF-1α mediated transcriptional activation of REDD1." (PMID 19587783, 2009). "For example, although the ATP-competitive mTOR inhibitor AZD8055 showed broad in vitro activity, its in vivo performance in ARMS was limited to disease progression without objective tumor regression." (PMID 40508013, 2025). "Everolimus, an mTOR inhibitor, augmented IRT damage of tumor vasculature in an in vivo mouse tumor model but no in vitro radiosensitization of tumor cells grown in cell cultures." (PMID 41498028, 2025). "By closely mimicking human tumor biology, PDX models enable the preclinical assessment of novel therapeutics, including PI3K/AKT/mTOR pathway inhibitors and chemotherapy regimens." (PMID 40072110, 2025). "The pharmacological inhibition of glycosphingolipid biosynthesis using eliglustat resulted in the down-regulation of p-mTOR and its downstream effector p-4E-BP1, in RAC1A159V mutant tumor cells but not in WT cells." (PMID 41160695, 2025). "By modulating gut microbiota metabolism to alter the host’s amino acid composition, BJO activates mTOR and exhibits microbiota-dependent inhibition of MDA-MB-231 xenograft tumor growth in mice, with no toxicity observed in non-target organs." (PMID 41156537, 2025). "In hepatocarcinogenesis, the PI3K/AKT/mTOR pathway often shows dysregulation, and PTEN, a negative regulator of this pathway, typically acts as a tumor suppressor." (PMID 39058151, 2024). "The inherent PD-1 binds to its ligand PD-L1 and activates the downstream mTOR signaling through PI3K/AKT-independent pathway, thereby promoting tumor cell self-proliferation, even in mice lacking adaptive immunity." (PMID 38762484, 2024). "Different signaling pathways have been reported to be modulated using AdipoRon, irrespective of the tumor type, such as mitogen-activated protein kinases (p42/p44 MAPK), AMPK and the mammalian target of rapamycin (mTOR)." (PMID 39123363, 2024). "In the subgroup of FIGO II-IV tumor tissue samples with available adjacent negative tissue controls (n = 26), both EGFR and p-mTOR (r = −0.450, p < 0.001) as well as p-mTOR and ER (r = 0.426, p < 0.001) expression demonstrated significant correlations." (PMID 37623437, 2023). "Immunohistochemistry (IHC) analyses showed that PI3K, AKT, p-AKT, p-mTOR, p-4E-BP1, P70S6K1, p-P70S6K1, eIF4E, and p-eIF4E proteins were significantly overexpressed in tumor tissues compared to adjacent non-tumoral tissues (p < 0.05 for all)." (PMID 37047267, 2023). "Even though a direct comparison of tumor response between each treatment was not feasible given the size of our cohort, the ORR and DCR observed for each mTOR inhibitor, and the other treatment modalities considered separately appeared to be similar." (PMID 37448552, 2023).
tumor (continued). "The effect remained stable in the subgroup (n = 41) of tumor samples with available matched negative controls (EGFR and PTEN r = 0.246, p = 0.009, EGFR and p-mTOR r = −0.207, p = 0.207; p-mTOR and ER r = 0.226, p = 0.014)." (PMID 37623437, 2023). "Collectively, our findings indicate that targeting mTOR rather than PI3K is more effective in reducing cell proliferation, tumor growth, cell migration, and stemness, independent of PIK3CA mutation status." (PMID 36792625, 2023). "Although as one might expect, more mutations were detected in the tumor tissue, including MTOR and BRCA1; however, the pathogenic PDGFRA variant (c.1939A > G, p.Ile647Val) was found in the urinary exosomes from both UC and NanoPoms preparations, but not in the tumor tissue cells." (PMID 35787656, 2022). "At the same time, they found that BEZ235 combined with Trichostatin A(histone deacetylase inhibitor) had better tumor inhibition effect than single drug.Clinical trials of dual PI3K and mTOR inhibitors have not been conducted in the ESCC." (PMID 35574327, 2022). "Strikingly, the protein complex formed by CHI3L1-Gal3 promotes the infiltration of “pro-tumour” M2 but not “anti-tumour” M1 macrophages and appears to be regulated transcriptionally by NF-κB/CEBPβ in the CHI3L1/Gal3/PI3K/Akt/mTOR axis." (PMID 36555253, 2022). "To investigate the mechanism of LF suppressing tumor growth in a high-glucose environment, we measured the expression of NT5DC3/PI3K/AKT/mTOR proteins in NCM460 cells co-cultured with HT29 cells in normal or high glucose conditions." (PMID 36553697, 2022). "The more prevalent actionable fusions identified were independent of tumour type in keeping with signalling via evolutionary conserved RAS/RAF/MEK/ERK, PI3K/AKT/MTOR, PLCy/PKC and JAK/STAT pathways." (PMID 35984852, 2022). "Myricetin has been demonstrated to modulate cell pathways essential for supporting tumor cell survival such as PI3K/Akt pathway, nrf signaling, canonical and non-canonical wnt pathway, mTOR pathway, Ras/Raf pathway and JAK/STAT pathway." (PMID 35902860, 2022). "In phase II studies, rapamycin, which is an FDA approved mTOR inhibitor, showed moderate prolongation of TTP (4 months) but did not decrease tumor size." (PMID 34359780, 2021). "With numbers of patients whose physical condition or tumor stage not suitable for radical surgery, they only have a narrow choice of using VEGF/mTOR targeted drugs to control their tumors, but ccRCC often shows resistance to these drugs." (PMID 34388114, 2021). "A phase I trial aimed to evaluate the preliminary anti-tumor effect, the safety profile/tolerability of BKM120 or BEZ235 (another PI3K/mTOR inhibitor) with Letrozole (non-steroidal aromatase inhibitor) used as endocrine therapy in post-menopausal MBC patients." (PMID 33801659, 2021). "CD36 has been reported to regulate PI3K/AKT signaling in tumor progression, but the exact interaction between APOC2 and CD36 as well as subsequent effect on PI3K/AKT/mTOR signaling in GC have not been investigated." (PMID 34459127, 2021). "A low level of TRP in the tumor microenvironment activates the general control non-derepressible 2 (GCN2) kinase, which prevents the phosphorylation of PKB and inhibits PKB/mTOR signaling." (PMID 34830312, 2021). "In one study on HNSCC cell lines and tumor xenografts, abemaciclib affected tumor growth and inhibited activation of AKT and ERK, but not mTOR." (PMID 33161487, 2021). "On the contrary to PI3K, mTOR, and MEK inhibitors that initiate growth but not tumor regression, the PARP inhibitor talazoparib led to significant regression in 5 of 12 PDXs." (PMID 34357119, 2021). "This also made it obvious, that the effect of the mTOR inhibition was a slow down of the proliferation in CEA424-SV40 T antigen transgenic mice, but not a cytotoxic effect on the tumor cells and a cure for the mice." (PMID 32373532, 2020).